HDAC3 (histone deacetylase 3)
Diseases named in the same sentence as HDAC3 in open-access papers (continued):
Sharing a sentence is not in itself a finding about the gene and the disease.
osteoarthritis (5 papers, 2019 to 2024). A noninflammatory degenerative joint disease occurring chiefly in older persons, characterized by degeneration of the articular cartilage, hypertrophy of bone at the margins and changes in the synovial membrane. "We found that ECM stiffening accelerated cultured chondrocyte senescence in vitro, while the stiffness ECM downregulated HDAC3, prompting Parkin acetylation to activate excessive mitophagy and accelerating chondrocyte senescence and osteoarthritis (OA) in mice." (PMID 38789434, 2024). "In a rat osteoarthritis model miR-326 delivered by BMSC-Exos, which targets HDAC3 and STAT1//NF-κB p65, can inhibit cartilage atrophy, thereby ameliorating osteoarthritis." (PMID 37427382, 2023). "On the whole, miR-326 targeting HDAC3 activates the STAT1/NF-κB p65 signaling pathway, inhibits the occurrence of pyroptosis, and protects chondrocytes from osteoarthritis." (PMID 34764819, 2021). "Exosomal miR-326 generated from BMSCs can target histone deacetylase 3 (HDAC3) and STAT1//NF-kB p65 to prevent chondrocyte and cartilage from pyroptosizing, transfer mir-326 to chondrocytes and cartilage, and reduce the symptoms of osteoarthritis." (PMID 36678850, 2023). "Matrix stiffening downregulates HDAC3 to activate phosphatase and tensin homolog-induced kinase 1 (PINK1) and Parkin (PINK1/Parkin) mediated mitophagy, thereby stimulating chondrocyte senescence and accelerating the initiation and progression of osteoarthritis." (PMID 38789434, 2024).
steatosis (5 papers, 2019 to 2024). Increased lipid within the cytoplasm of cells. "Notably, previous studies have shown that hepatocyte-specific deletion of histone deacetylase Hdac3 and Sirt1 leads to steatosis." (PMID 33376138, 2021). "Deletion of the HDAC3 gene causes disruption in lipid liver homeostasis and severe steatosis, while deletion of the REV-ERBβ gene does not cause significant disruption." (PMID 32344535, 2020). "Also, the deletion of HDAC3 in mice results in steatosis, inflammation and fibrosis." (PMID 32370249, 2020).
acute lymphoblastic leukemia (4 papers, 2011 to 2020). Leukemia with an acute onset, characterized by the presence of lymphoblasts in the bone marrow and the peripheral blood. "In acute lymphoblastic leukaemia patients, higher than median expression levels of HDAC3 were associated with a significantly lower 5-year event-free survival." (PMID 21346816, 2011). "In childhood acute lymphoblastic leukemia (ALL), high HDAC3 expression has been associated with a better prognosis, whereas overexpression of HDAC7 and 9 have been associated with a poorer prognosis." (PMID 26124919, 2015). "Likewise, low HDAC3, HDAC7 and HDAC9 expressions has been associated with poor prognosis and survival in childhood acute lymphoblastic leukemia (ALL)." (PMID 33024443, 2020). "Similarly, acute lymphoblastic leukemia (ALL) is characterized by increased contents of HDAC3 and 7, as compared to a normal bone marrow collection." (PMID 30875794, 2019).
adenomyosis (4 papers, 2022 to 2025). The growth of endometrial tissue inside the muscular wall of the uterine corpus. "In studies of adenomyosis, low expression of histone deacetylase 3 (HDAC3) has been negatively correlated with the degree of fibrosis, and reduced HDAC3 expression disrupts the NF-κB pathway, impairing the resolution of inflammation and endometrium repair and ultimately exacerbating the disease." (PMID 39595579, 2024). "Indeed, the expression of HDAC1 and HDAC3 was increased in the eutopic and ectopic endometrium of adenomyosis patients compared to controls." (PMID 37763670, 2023). "We demonstrated that estrogen repressed STING expression through the acetylation of STING DNA; HDAC3 is the key enzyme in estrogen-reduced STING expression, which is consistent with a previous study showing a correlation between NF-κB DNA-binding activity and dysmenorrhea severity in adenomyosis." (PMID 36230643, 2022).
Arthritis (4 papers, 2019 to 2024). Inflammation of a joint. "Regarding arthritis, most studies have focused on the involvement of HDAC3 in leptin-induced arthritis and synovitis in rheumatic arthritis, caused by metabolic dysfunction and autoimmunity dysfunction, respectively." (PMID 31481898, 2019). "Macrophage specific HDAC3 knockout (KO) mice were used to investigate inflammatory profiles of gout in mouse models in vivo, including ankle arthritis, foot pad arthritis and subcutaneous air pouch model." (PMID 38711064, 2024). "The effect of HDAC3 on RA-ILD in the constructed RA-ILD mouse model was also studied based on arthritis assessment." (PMID 33343379, 2020). "Osteoarthritis (OA) is another common form of arthritis in which HDAC3 plays a role." (PMID 39050859, 2024). "Also, both genetic and pharmacological inhibition of HDAC3 suppressed extracellular CIRP-induced abnormal activation of RA-FLS in vitro and RGFP966 treatment attenuated arthritis severity of adjuvant arthritis in rats, implicating a crucial role of HDAC3 in RA-associated synovial inflammation." (PMID 39050859, 2024).
atopic dermatitis (4 papers, 2018 to 2025). "The histone deacetylase HDAC3 was shown to act as a transcriptional repressor of IL-33 in multiple sclerosis patients and in a model of Staphylococcus aureus-aggravated skin inflammation associated to atopic dermatitis." (PMID 40317004, 2025). "The inhibition of HDAC3 by butyrate leads to a decrease in IL-33 expression and subsequently alleviates skin inflammation in a mouse model resembling atopic dermatitis." (PMID 38235133, 2023). "The data indicate that OFE, BSO, and especially their combination may reduce atopic dermatitis symptoms by inhibiting HDAC3/NF-κB signaling." (PMID 40612737, 2025). "Atopic dermatitis increased the expression levels of CD163, SOCS1, MIP-2, COX-2, HDAC3, COX-2, and MCP1 but decreased the expression of iNOS in a CXCL13-dependent manner." (PMID 30459600, 2018). "Atopic dermatitis increased the expression levels of SOCS1, TGaseII, COX-2, histone deacetylase 3 (HDAC3), and MCP1 in BALB/c mouse in an MIP-2-dependent manner." (PMID 30459600, 2018). "Atopic dermatitis increased the expression levels of MIP-2, COX-2, HDAC3, and MCP1 in BALB/c mice in a SOCS1-dependent manner." (PMID 30459600, 2018).
Autoimmunity (4 papers, 2011 to 2019). The occurrence of an immune reaction against the organism's own cells or tissues. "In vivo HDAC3 deletion in mouse Treg cells causes lethal autoimmunity, due to an upregulation of several inflammatory-related genes, revealing HDAC3 role in promoting Treg cell development and functional activity." (PMID 32117202, 2019). "Another study demonstrated that FOXP3+ regulatory T cell development and function require histone/protein deacetylase 3, and HDAC3-deficient mice died from autoimmunity by 4–6 weeks of age." (PMID 30402512, 2018). "Deletion of other HDAC enzymes, such as HDAC313 and HDAC534 impaired Treg function, and in the case of HDAC3 led to lethal autoimmunity." (PMID 28819166, 2017). "Increased expression of HDAC3 in PBMC of MS patients may render putative autoreactive lymphocytes resistance to apoptosis and thereby contribute to autoimmunity." (PMID 21346816, 2011).
cognitive decline (4 papers, 2017 to 2025). "Additionally, HDAC3‐mediated repression of transcription has been associated with cognitive decline both in aging and neurodegenerative diseases." (PMID 40662679, 2025). "This multifaceted role suggests that early HDAC3 inhibition offers an attractive mechanism to prevent HD cognitive decline and to suppress striatal expansions." (PMID 28729730, 2017).
cutaneous T cell lymphoma (4 papers, 2013 to 2022). "Previously, it was demonstrated that treatment of cutaneous T cell lymphoma (CTCL) cell lines (HH and Hut78) with a selective HDAC3 inhibitor caused a 50% reduction in DNA replication fork velocity and remarkable cell growth arrest." (PMID 35897717, 2022).
depression (4 papers, 2022 to 2025). "In individuals with stress-induced resilient depression, HDAC3 is extremely upregulated." (PMID 35251047, 2022).
endothelial dysfunction (4 papers, 2021 to 2024). In vascular diseases, endothelial dysfunction is a systemic pathological state of the endothelium (the inner lining of blood vessels) and can be broadly defined as an imbalance between vasodilating and vasoconstricting substances produced by (or acting on) the endothelium. "Collectively, these findings indicate that endothelial dysfunction caused by uncoupled eNOS was decreased by si-HDAC3 in HUVECs exposed to HG-PA." (PMID 33736642, 2021). "Because decreased nuclear Nrf2 signaling is associated with oxidative stress, we hypothesized that HDAC3 inhibition could protect against HG-PA-induced endothelial dysfunction by regulating Nrf2-modulated antioxidant gene expression." (PMID 33736642, 2021). "It has also been found that the mitigation of HDAC3 combats Type 2 diabetes mellitus-induced endothelial dysfunction via the Keap1-Nrf2-Nox4 signaling pathway." (PMID 38397377, 2024). "The results of this study suggest the potential of HDAC3 as a therapeutic target for the treatment of endothelial dysfunction in T2DM." (PMID 33736642, 2021). "The relationship between HDAC3 and endothelial dysfunction was examined by treating mice with the specific HDAC3 inhibitor RGFP966 by subcutaneous injection at a dose of 10 mg/kg." (PMID 33736642, 2021). "Next, we examined the effect of HDAC3 inhibition on eNOS uncoupling, which leads to endothelial dysfunction." (PMID 33736642, 2021). "Taken together, the results indicate that downregulation of Nox4 by HDAC3 inhibition protected against T2DM-induced endothelial dysfunction through a mechanism involving Nrf2 and the activation of the Nrf2–Nox4 negative feedback loop." (PMID 33736642, 2021). "In this study, we showed that HDAC3 inhibition decreases T2DM-induced endothelial dysfunction, thereby improving T2DM-induced injury in the vascular endothelium." (PMID 33736642, 2021).
esophageal tumor (4 papers, 2015 to 2023). "In line with our findings, esophageal tumor tissues showed upregulation of HDAC3 as compared to normal adjacent tissues, and conversely, its inhibition contributes to the arrested malignant properties of EC cells." (PMID 35578338, 2022). "SOX4 promotes esophageal tumor cell proliferation and invasion by silencing miR-31 via the activation and stabilization of a co-repressor complex with EZH2 and HDAC3." (PMID 34973135, 2023). "Clinically, compared to normal adjacent tissues, esophageal tumor samples showed an up-regulation of SOX4, EZH2, and HDAC3 in which the EZH2 expression was significantly increased in metastatic ESCC tissues." (PMID 34973135, 2023). "Clinically, when compared to normal adjacent tissues, esophageal tumor samples show upregulation of SOX4, EZH2, and HDAC3, and EZH2 expression is significantly increased in metastatic ESCC tissues." (PMID 25644061, 2015). "Here, we report that SOX4 promotes esophageal tumor cell proliferation and invasion by silencing miR-31 via activation and stabilization of a co-repressor complex with EZH2 and HDAC3." (PMID 25644061, 2015).
Glucose intolerance (4 papers, 2016 to 2024). Glucose intolerance (GI) can be defined as dysglycemia that comprises both prediabetes and diabetes. "Genetic deletion of HDAC3 in mouse models has been shown to improve glucose intolerance and insulin sensitivity in the liver, skeletal muscle, and adipose tissue." (PMID 37674539, 2023).
liver fibrosis (4 papers, 2023 to 2025). "Taken together, these results suggest that the loss of hepatic Hdac3 leads to liver fibrosis, potentially via ferroptosis." (PMID 38034086, 2023). "The expression levels of various proteins, specifically PIK3CB, AKT, pAKT, HDAC3, HDAC6, MMP9, MMP2, VIM, and α-SMA, which are implicated in hepatocyte degeneration as well as the initiation and progression of liver fibrosis, were analyzed using Western blotting." (PMID 39683581, 2024). "Thus, inhibiting ferroptosis reduces liver fibrosis in Hdac3-LKO mice." (PMID 38034086, 2023). "Indeed, we found that Hdac3-LKO mice have increased serum alanine transaminase (ALT) and aspartate transaminase (AST) levels, as well as increased Sirius red and Masson’s trichrome staining of liver sections, indicating liver fibrosis." (PMID 38034086, 2023).
mantle cell lymphoma (4 papers, 2017 to 2021). Mantle cell lymphoma is a rare form of malignant non-Hodgkin lymphoma affecting B lymphocytes in the lymph nodes in a region called the ``mantle zone''. "Indeed, it has been demonstrated that the Myc transcription factor, which is frequently dysregulated in almost all advanced cancers, has the potential to recruit HDAC3 in mantle cell lymphoma." (PMID 27935859, 2017). "HDAC3 interacts with Myc through the MBIIIa domain, and subsequently reduces miR-15a/16-1 level in mantle cell lymphoma (MCL) by anchoring at the two promoters of the miR-15a/16-1 cluster gene, DLEU2, and exerting repressive function." (PMID 34658888, 2021). "Two alkylating agents, bendamustine and a metabolite of cyclophosphamide (4-hydroperoxy-cyclophosphamide, 4-OHCY) induce H3K18 acetylation and decrease the expression of SIRT1, SIRT7, and HDAC3 in a dose-dependent manner in mantle cell lymphoma (MCL) cells." (PMID 31121824, 2019).
periodontitis (4 papers, 2022 to 2025). An acute or chronic inflammatory process that affects the tissues that surround and support the teeth. "Notably, HDAC3 activity is also essential for the transcriptional induction of several inflammatory mediators associated with periodontitis in GFs41." (PMID 41315835, 2025). "For example, it was shown that HDAC3 significantly reduced the expression of inflammatory mediators in gingival fibroblasts (GFs) from both healthy and diseased individuals in a model of periodontitis induced by TNF-α and Porphyromonas gingivalis." (PMID 39830512, 2024). "Treatment of both healthy and periodontally diseased gingival fibroblasts with pan-HDACi or HDAC3/6i prior to P. gingivalis infection significantly reduced the induction of a subset of inflammatory mediators (CCL2, CCL5, CXCL10, IL1B, COX2 and MMP3) implicated in periodontitis." (PMID 36291079, 2022).
rhabdomyosarcoma (4 papers, 2020 to 2025). A rare aggressive malignant mesenchymal neoplasm arising from skeletal muscle. "We previously reported that the nuclear HDACs (HDAC1, HDAC2 and HDAC3) were co-essential in maintaining CR TF circuits in rhabdomyosarcoma." (PMID 41392987, 2025). "NCoR/SMRT-HDAC3 complexes also inhibit differentiation of rhabdomyosarcoma cells in an HDAC3 activity-dependent manner that involves the deacetylation of histone 3 K9." (PMID 35632695, 2022).
triple-negative breast carcinoma (4 papers, 2019 to 2023). An invasive breast carcinoma which is negative for expression of estrogen receptor (ER), progesterone receptor (PR), and human epidermal growth factor receptor 2 (HER2). "Furthermore, an HDAC3-selective inhibitor was shown to suppress the growth of triple-negative breast cancer stem cells in vitro and in vivo." (PMID 31430896, 2019).
acute kidney injury (3 papers, 2024 to 2025). Sudden and sustained deterioration of the kidney function characterized by decreased glomerular filtration rate, increased serum creatinine or oliguria. "In acute kidney injury, histone deacetylase 3(HDAC3) mutations can cause GPX4 inhibition, promote ferroptosis of renal epithelial cells, and aggravate AKI development." (PMID 40959280, 2025). "Instructively, treatment with the HDAC3 selective inhibitor RGFP966 exerted potent protective effects, attenuates acute kidney injury in both in vivo and in vitro models." (PMID 40351427, 2025).
acute promyelocytic leukemia (3 papers, 2021 to 2024). An aggressive form of acute myeloid leukemia (AML), characterized by arrest of leukocyte differentiation at the promyelocyte stage, due to a specific chromosomal translocation t(15;17) in myeloid cells. "HDAC3 was reported to be an important player in the development of acute promyelocytic leukemia, and knockdown of HDAC3 can inhibit the PI3k/Akt-mediated signaling pathways and the induction of Caspase activity, thus leading to cell death and apoptosis." (PMID 37553641, 2023). "Deregulated HDAC3 acts as a crucial role in the progress of acute promyelocytic leukemia (APL) with PML-RARα fusion protein." (PMID 34540702, 2021).
age (3 papers, 2015 to 2024). A temporal measurement of the time period elapsed since an identifiable point in the life cycle of an organism. "We show that blocking HDAC3 immediately after updating with the pharmacological inhibitor RGFP966 ameliorated age-related impairments in memory updating in 18-m.o." (PMID 38989157, 2024). "Overall, this suggests that HDAC3 regulates the strength of the memory update and contributes to age-related impairments in memory updating." (PMID 38989157, 2024). "Here, we tested whether HDAC3 also contributes to age-related impairments in memory updating using the Objects in Updated Locations (OUL) paradigm." (PMID 38989157, 2024). "Further, it is also unclear whether HDAC3 also contributes to age-related impairments in memory updating." (PMID 38989157, 2024). "Overall, our findings show that HDAC3 regulates the competition between an original memory and a memory update and suggest that HDAC3 may contribute to age-related impairments in memory updating." (PMID 38989157, 2024). "Abnormal HDAC3-mediated repression of Per1 in the aging brain is therefore a key event that could lead to age-related impairments in both long-term memory formation and circadian rhythmicity." (PMID 30127461, 2018). "One potential mechanism is the repressive histone deacetylase 3 (HDAC3), which is a powerful negative regulator of memory formation that contributes to age-related impairments in memory formation." (PMID 38989157, 2024). "Together, these results demonstrate that blocking HDAC3 with RGFP966 immediately after an update can ameliorate age-related impairments in memory updating without affecting the original memory." (PMID 38989157, 2024).
aristolochic acid nephropathy (3 papers, 2021 to 2024). "Studies have shown that HDAC3 is abnormally active in fibrotic kidneys caused by unilateral ureteral obstruction (UUO) and aristolochic acid nephropathy (AAN), and its deletion can promote the expression of klotho to fight against kidney fibrosis." (PMID 37362429, 2023). "Concurrently, HDAC3 is upregulated by the TGF-β/SMAD pathway in mouse models of UUO, aristolochic acid nephropathy (AAN), and adenine-induced CKD." (PMID 38929505, 2024).
autoimmune disease (3 papers, 2011 to 2020). A disorder resulting from loss of function or tissue destruction of an organ or multiple organs, arising from humoral or cellular immune responses of the individual to their own tissue constituents. "When compared to studies in cancer, expression of HDAC3 and its role in autoimmune disease has received limited attention." (PMID 21346816, 2011). "Thus, our findings may shed light on HDAC3 as a potential therapeutic target for AM-based intervention in cancer and autoimmune diseases." (PMID 32732898, 2020). "WhileHDAC3 powerfully regulates STAT1 activity in RA-FLS, indicating HDAC3 as a potential therapeutic target in the treatment of RA and type I IFN-driven autoimmune diseases." (PMID 30884802, 2019). "While increased expression of HDAC3 is seen in neoplastic cells, the role of HDAC3 in T cells and their role in autoimmune disease is not known." (PMID 21346816, 2011).